KL (klotho)
Diseases named in the same sentence as KL in open-access papers (continued):
Sharing a sentence is not in itself a finding about the gene and the disease.
hepatocellular carcinoma (16 papers, 2013 to 2025). A malignant tumor that arises from hepatocytes. "In our present study, immunohistochemical Klotho staining levels in a clinical follow-up of 52 hepatoma patients were significantly associated with liver cirrhosis, tumor multiplicity and venous invasion." (PMID 23516476, 2013). "Several groups reported a downregulation of Klotho in hepatocellular carcinoma (HCC) and Klotho deficiency in patients with HCC correlates with poor survival." (PMID 29799477, 2018). "In the present study, we found for the first time that high immunohistochemical Klotho staining levels were significantly associated with liver cirrhosis, tumor multiplicity, venous invasion, and poor overall survival in a clinical follow-up of 52 hepatoma patients." (PMID 23516476, 2013). "For example, in hepatocellular carcinoma, KL suppresses Wnt/β-catenin signaling, reducing cell proliferation." (PMID 40004457, 2025). "Previous studies have also demonstrated that KL is downregulated in several cancers, such as pancreatic cancer and hepatocellular carcinoma (HCC)." (PMID 36091132, 2022). "In recent years, many studies have reported Klotho as an oncogene in several tumors, including hepatocellular carcinoma." (PMID 34239888, 2021). "HCC tumor-bearing mice receiving intratumoral injections of soluble Klotho twice weekly for 4 weeks exhibited a significant reduction in tumor size compared to saline controls, demonstrating that Klotho is a tumor suppressor in hepatocellular carcinoma." (PMID 29799477, 2018). "Forced overexpression of Klotho decreased proliferation of hepatoma cells by preventing downstream Wnt signaling." (PMID 29799477, 2018). "Cell migration assay demonstrated that ectopic expression of Klotho increased hepatoma cell migration." (PMID 23516476, 2013). "TUNEL assay revealed that increased anoikis by VEGFR2 inhibitor Axitinib or its blocking antibody was partially blunted by PAK1 activation with PAK1 T423E cotransfection in Klotho-overexpressed hepatoma cells." (PMID 23516476, 2013). "Taken together, these results suggest that VEGFR2/PAK1 signaling dominates Klotho-induced resistance of hepatoma cells to anoikis." (PMID 23516476, 2013). "The overall survival rate of hepatoma patients with high Klotho expression was significantly lower than those patients with low Klotho expression." (PMID 23516476, 2013). "Caspase 3/7 activity assay revealed that increased anoikis by VEGFR2 inhibitor Axitinib or its blocking antibody was partially reversed by PAK1 activation with PAK1 T423E cotransfection in Klotho-overexpressed hepatoma cells." (PMID 23516476, 2013). "Klotho expression was found to increase VEGFR2 protein level in hepatoma cells suggesting the potential function of VEGFR2 in Klotho-mediated anoikis resistance." (PMID 23516476, 2013). "Colony formation assay showed that inhibited anchorage-independent growth by VEGFR2 inhibitor Axitinib or its blocking antibody was partially reversed by PAK1 activation with PAK1 T423E cotransfection in Klotho-overexpressed hepatoma cells." (PMID 23516476, 2013). "Annexin V/PI staining, Caspase 3/7 activity assay, and TUNEL assay in suspended hepatoma cells showed that Klotho-induced anoikis resistance was reversed by inactivating PAK1 kinase activity with PAK1 K299R cotransfection or IPA3 treatment." (PMID 23516476, 2013). "Colony formation assay showed that increased anchorage-independent growth of hepatoma cells due to Klotho expression was reversed by inactivating PAK1 kinase activity with PAK1 K299R cotransfection or IPA3 treatment." (PMID 23516476, 2013). "Elevated caspase 3/7 activities after detachment in these two hepatoma cells were significantly rescued by Klotho expression." (PMID 23516476, 2013). "Colony formation assay showed that increased anchorage-independent growth of hepatoma cells due to Klotho expression were reversed by VEGFR2 inhibition with VEGFR2 inhibitor Axitinib or its blocking antibody." (PMID 23516476, 2013).
hepatocellular carcinoma (continued). "Caspase 3/7 activity assay and TUNEL assay in suspended hepatoma cells showed that Klotho-induced anoikis resistance was reversed by VEGFR2 inhibition with VEGFR2 inhibitor Axitinib or its blocking antibody." (PMID 23516476, 2013). "Axitinib treatment sensitized anoikis was reversed by constitutive active mutant PAK1 T423E coexpression in Klotho-overexpressed hepatoma cells." (PMID 23516476, 2013). "The KL gene expression and the promoter DNA methylation predict a poor prognosis in HCC, suggesting that the Klotho gene might be a therapeutic target for hepatocellular carcinoma treatment." (PMID 40004457, 2025). "Klotho acts as a tumor suppressor in hepatocellular carcinoma through several mechanisms." (PMID 40004457, 2025). "Also, in a recent study, the Klotho expression in hepatocellular carcinoma was a marker of a good prognosis." (PMID 36009045, 2022). "In addition, hypermethylation of KLOTHO was shown to low expression in hepatocellular carcinoma tissues." (PMID 26197428, 2015). "Since anoikis resistance is prerequisite for hepatoma progression and metastasis, resistance of hepatoma cells to anoikis due to Klotho expression might be the crucial functional role of Klotho in HCC development and progression." (PMID 23516476, 2013). "Consistent with our previous studies indicating the pivotal significance of PAK1-induced anoikis resistance in HBV-associated hepatocarcinogenesis, our current data also indentify VEGFR2/PAK1 activation as downstream effector of Klotho expression in anoikis resistance of hepatoma cells." (PMID 23516476, 2013). "Moreover, Kaplan-Meier survival analysis indicated that the overall survival rate of hepatoma patients with high Klotho expression was significantly lower than those with low Klotho expression (P = 0.03)." (PMID 23516476, 2013). "The present study demonstrates that Klotho expression is significantly associated with tumor aggressiveness and poor overall survival in a clinical follow-up of 52 hepatoma patients, indicating the potential oncogenic function of Klotho in hepatocarcinogenesis." (PMID 23516476, 2013). "Moreover, colony formation assay revealed that Klotho expression promoted significantly anchorage-independent growth of hepatoma cells." (PMID 23516476, 2013). "Klotho overexpression elevated p21-activated kinase 1 (PAK1) expression and shRNA-mediated PAK1 knockdown and kinase activity inhibition with kinase dead mutant PAK1 K299R coexpression or allosteric inhibitor IPA3 treatment reversed anoikis resistance in Klotho-overexpressed hepatoma cells." (PMID 23516476, 2013). "Moreover, Klotho overexpression increased cellular migration, anchorage-independent growth, and anoikis resistance in hepatoma cells." (PMID 23516476, 2013). "Although we have identified that Klotho expression confers hepatoma cells with resistance to anoikis through VEGFR2/PAK1 activation, the underlying molecular mechanism for Klotho-mediated VEGFR2/PAK1 activation remains still obscure and needs further exploration." (PMID 23516476, 2013). "Tissue expression of Klotho using IHC has also been shown to inversely correlate with the histological grade and clinical stage of patients with hepatocellular carcinoma (HCC)." (PMID 32585905, 2020). "For example, in cultures of the human hepatoma cell lines HepG2 and MHCC-97-H, restoration of Klotho significantly inhibited their cell proliferation." (PMID 34737707, 2021). "Besides, we have also provide evidence that VEGFR2/PAK1 inhibition with VEGFR2 inhibitor Axitinib, or anti-VEGFR2 blocking antibody, or PAK1 allosteric inhibitor IPA3 administration could significantly blunt anoikis resistance in Klotho-overexpressed hepatoma cells." (PMID 23516476, 2013). "More importantly, the pivotal significance of upregulated VEGFR2 protein levels mediated by Klotho expression was confirmed by VEGFR2 inhibitor Axitinib and blocking antibody treatment in hepatoma cells." (PMID 23516476, 2013).
hepatocellular carcinoma (continued). "We also provide evidence that Klotho expression confers hepatoma cells with resistance to anoikis via activating VEGFR2/PAK1 signaling, which could be reversed by inhibition with PAK1 allosteric inhibitor IPA3 or VEGFR2 inhibitor Axitinib administration in Klotho-overexpressed hepatoma cells." (PMID 23516476, 2013). "Furthermore, Klotho expression conferred hepatoma cells with resistance to anoikis via activating VEGFR2/PAK1 signaling, which could be reversed by inhibition with PAK1 allosteric inhibitor IPA3 or VEGFR2 inhibitor Axitinib administration in Klotho-overexpressed hepatoma cells." (PMID 23516476, 2013).
hypophosphatemia (16 papers, 2011 to 2025). Lower than normal levels of phosphates in the circulating blood. "Conversely, excessively high levels of circulating Klotho are associated with hypophosphatemia and hypocalcemia, increased FGF23 production, bone rarefaction, osteomalacia and fractures." (PMID 32640692, 2020). "However, emerging evidence from clinical trials has revealed that klotho therapies may disrupt Ca2+ homeostasis by controlling parathyroid hormone (PTH) secretion, and intravenous infusion of klotho may also cause hypophosphatemia and phosphaturia." (PMID 36120595, 2022). "Recently, it has been noted that Hyp/klotho-/- knockout mice lack the hypophosphatemia and mineralization defects of Hyp, but with a shortened life span." (PMID 21854633, 2011). "In our study, the very mild increase in Fgf23 levels and the lack of hypophosphatemia suggests that the phenotypic differences in response to glomerular injury is indeed caused by soluble Klotho, and not by elevated Fgf23 and/or lower phosphate." (PMID 36813870, 2023). "Thus, regaining function in FGF23-Klotho signaling after KTx helps promote urinary phosphate excretion and reduced vitamin D-dependent intestinal absorption of calcium and phosphate, which might explain the association between post-KTx hypophosphatemia and reduced cardiovascular mortality." (PMID 32545510, 2020). "Additionally, treatment with an adeno-associated virus that produced Klotho resulted in increased circulating serum Klotho and caused FGF23-related hypophosphatemia in mice." (PMID 30627598, 2019). "Klotho does not appear to be toxic, but higher than normal levels (as seen in rare human diseases) can induce hypophosphatemia and other negative effects." (PMID 39272986, 2024). "Following successful KTx, patients regain functions of klotho via FGF23-Klotho signaling, and with the previously accumulated FGF23, residual hyperparathyroidism, and the use of calcineurin inhibitors (especially cyclosporine), post-KTx hypophosphatemia can commonly occur up to 86%." (PMID 32545510, 2020). "The results of our study challenge existing paradigms in mineral homeostasis; our data provide evidence that hypophosphatemia can develop in the absence of serum changes in the phosphaturic hormones, PTH and FGF-23 and despite declining serum Klotho levels." (PMID 32634148, 2020).
myocardial infarction (16 papers, 2016 to 2025). Gross necrosis of the myocardium, as a result of interruption of the blood supply to the area, as in coronary thrombosis. "A positive association was only found between Klotho levels and the previous occurrence of a myocardial infarction by both correlational (p=0.006) and variance analyses (p<0.001), and these associations were independent of the context." (PMID 28076518, 2016). "Surprisingly, there was higher concentration of serum Klotho in patients with myocardial infarction in the past." (PMID 30671457, 2018). "The compensatory synthesis of Klotho was also found in patients after myocardial infarction." (PMID 41574188, 2025). "Interestingly, increased levels of Klotho reduce oxidative damage after myocardial infarction in animal models." (PMID 37061530, 2023). "Given the apparent importance of Klotho, it may be considered as a novel vital factor in the ischemic heart injury, such as myocardial infarction." (PMID 30671457, 2018). "This study investigated Klotho as a biomarker and potential novel treatment of IHD‐associated complications after myocardial infarction (MI) under preserved renal function." (PMID 39815421, 2025).
sarcopenia (16 papers, 2020 to 2026). Progressive decline in muscle mass due to aging which results in decreased functional capacity of muscles. "Low Klotho is associated with loss of muscle mass (sarcopenia), as occurs in aging and chronic diseases." (PMID 39272986, 2024). "Klotho-deficient mice (kl/kl) have marked muscle atrophy (sarcopenia)." (PMID 39272986, 2024). "Klotho-deficient mice have sarcopenia and decreased bone density." (PMID 32102215, 2020). "Klotho also protects against muscle atrophy (sarcopenia)-a common feature of aging-and exhibits anti-cancer activity." (PMID 41892298, 2026). "In summary, our research findings indicate that deferiprone reduced age‐related sarcopenia in the muscles of Klotho−/− mice." (PMID 39797505, 2025). "In another study in 2023, klotho protein can treat sarcopenia by inhibiting transforming growth factor β through binding to ligands and type I and type II serine/threonine kinase receptors." (PMID 40452763, 2025). "Other biomarkers bridging CKD, sarcopenia, and aging are represented by Klotho protein, AGEs, and vitamin D." (PMID 39055699, 2024). "Homozygous mutant Klotho (KL-/-) mice display a variety of premature aging phenotypes, including emphysema and sarcopenia, and their lifespan is considerably shortened." (PMID 37614743, 2023). "Taken together, these results suggest Klotho enhances skeletal muscle structure and function at the early stages of sarcopenia, but the beneficial effects are lost after the entropic inflection point." (PMID 33876724, 2021). "In summary, several pathophysiological mechanisms of sarcopenia are regulated by the extrarenal functions of Klotho, including muscle satellite cell function, mitochondrial function, oxidative stress, and inflammation." (PMID 36188832, 2021). "Emerging data support the existence of Klotho-related benefits to exercise and for potential Klotho-based therapeutic interventions for the treatment of sarcopenia and its progression to physical disability." (PMID 36188832, 2021). "Taken together, these studies suggest an unexplored mechanistic link between sarcopenia and a decline of Klotho with increasing age." (PMID 33876724, 2021). "Elucidating the mechanisms of Klotho signaling in skeletal muscle may provide additional opportunities for the development of treatments that can address the increasing burden of sarcopenia and its progression to physical disability." (PMID 38169578, 2024). "The authors postulated that s-Klotho counteracts TGF-β-induced sarcopenia." (PMID 39272986, 2024). "Elucidating the mechanisms of Klotho signaling in skeletal muscle may provide additional opportunities for treatment developments that can address the growing burden of sarcopenia and its progression to physical disability." (PMID 36188832, 2021). "No study to date, however, has evaluated the relationship between Klotho levels and telomere length in skeletal muscle or whether skeletal muscle telomere length in vivo plays a role in the development of sarcopenia in aging and CKD." (PMID 36188832, 2021). "Potential associations between sarcopenia and KLOTHO polymorphisms had not been previously studied before, so the lack of such associations revealed by our study consists in negative but novel information." (PMID 32444684, 2020). "Furthermore, given its correlations with muscle mass and quality, Klotho may represent the biomolecular link between sarcopenia and CKD." (PMID 39055699, 2024). "Moreover, research in animal models suggests that Klotho-based therapy may enhance muscle function and reverse sarcopenia." (PMID 36188832, 2021). "We then tested the ability of AAV-mediated Klotho delivery (AAV-Kl) to attenuate these changes and counteract sarcopenia in old and oldest-old mice." (PMID 33876724, 2021).
sarcopenia (continued). "The reduction in muscle mass in Klotho deficient mice was concomitant with the increased muscle expression of ubiquitin ligases, suggesting that Klotho deficient mice are likely undergoing sarcopenia-like muscle wasting rather than a developmental defect in skeletal muscle growth." (PMID 36188832, 2021). "However, no studies have investigated the role of nutritional supplementation of the Klotho protein expression to improve muscle size or physical performance in patients with COPD and sarcopenia." (PMID 37614743, 2023). "The pro-longevity effects of Klotho have been partially attributed to modulation of fibroblast growth factor 23 (FGF23), Wnt, and mTOR pathways, several of which have also been a targets in sarcopenia research." (PMID 33876724, 2021). "Third, since this is an exploratory study and not conducted to specifically investigate the association between phosphorus regulation and sarcopenia, we did not study factors influencing phosphorus regulation, such as FGF23, klotho, vitamin D, parathyroid hormone, and dietary intakes." (PMID 32438707, 2020). "Notably, the anti-aging effects of Klotho have been partially attributed to modulation of the renin-angiotensin system (RAS), Wnt, mammalian target of rapamycin (mTOR), and mitogen-activated protein kinase (MAPK) pathways, some of which are also mechanistic targets for these sarcopenia treatments." (PMID 36188832, 2021).
skin atrophy (16 papers, 2010 to 2024). The degeneration and thinning of the epidermis and dermis. "Mice with the mutation of the klotho gene showed features of aging, such as short life span, infertility, and skin atrophy, whereas klotho-overexpressed mice had increased life span." (PMID 35666743, 2022).